IL6 (interleukin 6)
Diseases named in the same sentence as IL6 in open-access papers (continued):
Sharing a sentence is not in itself a finding about the gene and the disease.
endothelial dysfunction (continued). "Elevated interleukin-6 (IL-6) and activated nuclear factor-kappa B (NF-κB) alter vascular homeostasis by increasing vascular permeability, enhancing monocyte adhesion, and promoting smooth muscle cell proliferation, contributing to endothelial dysfunction and plaque formation." (PMID 39517211, 2024). "However, the use of biochanin A improved IL-6 induced endothelial dysfunction." (PMID 38195507, 2024). "Besides, releases of proinflammatory cytokines such as interleukin (IL)-6 and tumor necrosis factor (TNF)-α could induce endothelial dysfunction, which was also associated with incident CKD." (PMID 38172903, 2024). "A recent study reported several pathogenic models through which RT may induce cardiac toxicity, including an inflammatory response mediated by pro-inflammatory cytokines, such as tumor necrosis factor-alpha (TNF-α), interleukin-1 (IL-1) and interleukin-6 (IL-6); endothelial dysfunction and fibrosis." (PMID 39469128, 2024). "Therefore, we speculate whether biochanin A can reduce the expression of IL-6, inhibit inflammation, improve IL-6 induced endothelial dysfunction, and promote femoral head vascular reconstruction." (PMID 38195507, 2024). "First, fibrinogen may upregulate the proinflammatory cytokines interleukin-6 and tumor necrosis factor-α, thus exacerbating vascular inflammation and endothelial dysfunction; in turn, this could result in the formation of atherosclerotic plaques and plaque vulnerability." (PMID 37305748, 2023). "Endothelial dysfunction can also be induced by infection; chronic periodontal infection induces endothelial activation or dysfunction by a systemic inflammatory state evidenced by elevated plasma levels of acute phase protein, interleukin (IL)-6, and fibrinogen." (PMID 37374981, 2023). "IL-6 modulates vascular function by upregulating the mRNA expression of the angiotensin II type 1 receptor, which then leads to greater angiotensin II-mediated vasoconstriction, greater free oxygen radical production (in vitro and in vivo), and the onset of endothelial dysfunction." (PMID 35682871, 2022). "Endothelial dysfunction, oxidative stress, VSMCs macrophage foam cells accumulation, toll-like receptor signaling, NLPR-3 inflammasome formation, and subsequent pro-inflammatory cytokine production, such as TNF-α, IL-1β, IL-6 are few of the mechanisms implicated in the atherogenic process." (PMID 35805095, 2022). "Thus, the pre-disposition of MSK1/ 2 KO mice to produce increased levels of IL-6 may directly mediate the observed endothelial dysfunction through altered eNOS signaling." (PMID 34445361, 2021). "In endothelial dysfunction, activation of the nuclear factor-kappa B (NF-κB) pathway has highlighted elevated levels of pro-inflammatory cytokines such as tumor necrosis factor-alpha, interleukin-1beta (IL-1 β), interleukin-6 (IL-6), and interferon gamma (IFN-γ)." (PMID 33467601, 2021). "Furthermore, hypertension induced by pro-inflammatory status, increasing IFN-γ, IL-6, and IL-17 expression and CD8 + T cells in the kidney, angiotensin II-induced hypertension, and the endothelial dysfunction caused by the innate immune response seems to be involved in the kidney injury." (PMID 33781275, 2021). "Pro-inflammatory cytokines such as TNF-α, IL-6, IL-8, and IL-18 are essential inflammatory mediators, aggravating the inflammatory response and inducing the expression of adhesion molecules in endothelial cells and leukocytes (E-selectin, and P-selectin), which worsen endothelial dysfunction." (PMID 33917744, 2021). "Besides, values of plasma biomarkers linked to inflammation (inflammatory response and endothelial dysfunction) were related to the severity of liver cirrhosis (CTP score), mainly IP-10 and IL-6, which discriminated patients with Child-Pugh B concerning Child-Pugh A." (PMID 32587340, 2020).
endothelial dysfunction (continued). "These patients may not require a high degree of systemic inflammation and endothelial dysfunction to develop delirium, which may explain the lack of associations between IL-6, IL-8, and PAI-1 and ED delirium duration." (PMID 31856187, 2019). "Furthermore, several studies have reported that an intensive periodontal treatment resulted not only in a temporary increase in serum levels of CRP and IL-6, but also in a significant improvement of endothelial dysfunction indexes at six months after active periodontal therapy." (PMID 31817862, 2019). "Moreover, the link between endothelial dysfunction and inflammatory cytokine production has been emphasized by studies that attribute increased IL-6 production to mechanical endothelial stretch in hypertensive individuals, with a subsequent decrease in NO production." (PMID 31186952, 2019). "Additionally, we hypothesised that both IL–6 and sCD163 independently drive excess endothelial dysfunction among HIV–infected participants." (PMID 29771268, 2018). "We also report a lack of association between sCD163 and VCAM–1 for the first time in a SSA clinical cohort, replicating what has been observed in non–African cohorts, and we corroborate a previously demonstrated lack of association between IL–6 and cIMT with endothelial dysfunction in this setting." (PMID 29771268, 2018). "Besides their deleterious effects on the kidneys, inflammatory cytokines such as IL-6 exert a direct detrimental effect on the myocardial structure and function by promoting oxidative stress and endothelial dysfunction, thus contributing to the progression of HF29." (PMID 29942050, 2018). "Finally, our immunofluorescence data showing higher expression of IL-6 protein in coronary endothelium compared to the WT mice support our conclusion that IL-6-mediated endothelial dysfunction is induced by attenuated NO signaling pathways in endothelial cells." (PMID 29095915, 2017). "Alternatively, higher concentrations of inflammatory and endothelial dysfunction markers among lymphoma patients including interleukin 6 are significantly correlated with decreased AMH concentrations as well as CVD risk, suggesting that AMH may also be linked with CVD through this pathway." (PMID 30766706, 2017). "Furthermore, endothelial dysfunction and the following arterial stiffness have been related to the synergistic effect of smoking with inflammatory molecules of interleukin-6 (IL-6), C-reactive protein (CRP), and cyclooxygenase-1 and cyclooxygenase-2 (COX-1 and COX-2)." (PMID 26885247, 2016). "In addition to the modifying effect of TFAs on the lipid profile, dietary intake of TFAs has been associated with an increase in markers of endothelial dysfunction such as CRP, interleukin-6, soluble tumor necrosis factor receptor 2, E-selectin and soluble cell adhesion molecules." (PMID 26920731, 2016). "Dessein and Joffe reported significant reductions of IL-6 after 2 weeks of high-dose intra-articular methylprednisolone combined with DMARDs, associated with a decrease in markers of endothelial dysfunction, without significant changes in other inflammatory cytokines such as IL-1 and TNF-α." (PMID 24864133, 2014). "However, the model is well-documented with a small rise in IL-6 with a magnitude similar to the rise associated with non-ST-elevation myocardial infarction with cardiovascular consequences, such as endothelial dysfunction, increased vascular stiffness and activation of coagulation factor VII." (PMID 41403875, 2026). "Inflammatory mediators such as IL-6, TNF-α, and IL-1β play a crucial role in cardiovascular disease, particularly in the pathogenesis of atherosclerosis, endothelial dysfunction, and CVD." (PMID 41601490, 2026). "Endpoints assessed included mean changes in plasma inflammatory markers (IL-1β, IL-6, and TNF-α) and endothelial dysfunction markers (syndecan-1), handgrip strength, fatigue scale, and quality of life (QoL)." (PMID 41753154, 2026).
endothelial dysfunction (continued). "Some authors reported that elevated levels of IL-1β, IL-6, and TNF-α not only function as immune effectors but also contribute to endothelial dysfunction, increased vascular permeability, and metabolic disturbances when produced excessively." (PMID 40806937, 2025). "Endothelial dysfunction induced by tumour necrosis factor (TNF) and platelet activation triggered by interleukin-6 (IL-6) lead to tissue factor expression on platelets and monocytes, enhancing thrombin generation and fibrin formation." (PMID 40943137, 2025). "Cytokines such as interleukin-1β (IL-1β) and interleukin-6 (IL-6) further stimulate hepatic production of acute-phase proteins such as C-reactive protein (CRP), contributing to endothelial dysfunction in systemic blood vessels." (PMID 41444986, 2025). "The IL-6 and TNF-α reduction is particularly significant given the established roles of these cytokines in endothelial dysfunction and vascular inflammation." (PMID 40735328, 2025). "Despite increasing recognition of the role of inflammation and endothelial dysfunction in CKD, evidence on the combined impact of IL-6, ADMA, and related biomarkers on cardiac remodeling remains limited." (PMID 41450363, 2025). "Mechanically, IR-related markers could increase endothelial dysfunction by activating NF-κB or PI3K/Akt signaling pathways, increasing reactive oxygen species (ROS) production, and secreting proinflammatory cytokines (TNF-α, IL-6, IL-1β), to further improve cardiovascular disease risk." (PMID 41450551, 2025). "Systemic inflammation, as indicated by elevated levels of cytokines like interleukin-6 (IL-6) and high-sensitivity C-reactive protein (hs-CRP), plays a critical role in endothelial dysfunction, microvascular rarefaction, and structural myocardial alterations." (PMID 40065867, 2025). "Early stages: Inflammation-related genes (e.g., IL6, TNF-α) show significantly elevated expression, reflecting endothelial dysfunction and inflammatory infiltration." (PMID 39858645, 2025). "Moreover, we focused primarily on inflammatory and hematologic indices; the addition of emerging markers of endothelial dysfunction (e.g., endothelin-1, von Willebrand factor) or systemic inflammation (e.g., interleukin-6, C-reactive protein) may enhance prognostic stratification." (PMID 41303423, 2025). "Systemic inflammation increases cytokine levels (e.g., IL-6, TNF-α), promoting coagulation and endothelial dysfunction." (PMID 39857281, 2025). "The systemic inflammatory cascade is driven by cytokines such as interleukin-6 (IL-6), tumor necrosis factor-alpha (TNF-α), and interleukin-1β (IL-1β), leading to tissue injury, endothelial dysfunction, and multi-organ failure." (PMID 40959673, 2025). "Elevated levels of circulating pro-inflammatory cytokines, such as IL-6, TNF-α, and IL-1β, create a sustained inflammatory milieu that exacerbates vascular oxidative stress and accelerates endothelial dysfunction." (PMID 40113668, 2025). "IL-32 contributes to vascular inflammation by inducing IL-6 and TNF-α, enhancing endothelial dysfunction and pro-atherogenic lipid changes." (PMID 40937212, 2025). "Elevated concentrations of IL-6 (pg/mL), homocysteine (μmol/L), ADMA (ng/mL), uric acid (mg/dL), and NT-proBNP (pg/mL) reflect systemic inflammation, endothelial dysfunction, metabolic abnormalities, and cardiac strain in patients with chronic kidney disease." (PMID 41450363, 2025). "Additionally, the release of several cytokines in GBS (tumor necrosis factor-α, interleukin-6, interferon-γ, and IL-17) responsible for systemic immune activation, which, in our hypothesis, could lead to endothelial dysfunction and altered vascular permeability, is seen in PRES." (PMID 40988737, 2025). "Inflammatory cytokines like IL-1β, IL-6, and TNF-α are elevated following SAH, driving endothelial dysfunction and blood-brain barrier breakdown, which can worsen brain injury." (PMID 40783564, 2025).
endothelial dysfunction (continued). "Compared to IL-6 and TNF-α, which primarily indicate systemic inflammation, VCAM-1 is a more specific marker of endothelial dysfunction." (PMID 40385768, 2025). "Indirect mechanisms include systemic inflammation (elevated seminal IL‐6/TNF‐α), febrile insults during spermiogenesis, and endothelial dysfunction leading to erectile dysfunction (eNOS reduction, perivascular viral particles)." (PMID 41293404, 2025). "The hierarchical analysis demonstrates that TNF-α retains its prognostic value for predicting MACE after accounting for endothelial dysfunction (FMD) and systemic inflammation (IL-6)." (PMID 40310443, 2025). "This study highlights the interplay between atherogenic status (e.g., elevated LDL-C), systemic inflammation (e.g., IL-6, hs-CRP), and coagulation-related endothelial dysfunction (e.g., sCD40-L, VCAM-1), which collectively contribute to CMVO pathogenesis." (PMID 40988197, 2025). "Excessive release of pro-inflammatory cytokines (e.g., IL-6, IFN-γ) leads to endothelial dysfunction, hypotension, myocardial depression, arrhythmias, and acute coronary syndromes." (PMID 40606990, 2025). "Produced by immune, renal, and endothelial cells; drives IL-1β/IL-6 via NF-κB and MAPK; ↑ endothelial dysfunction and proteinuria." (PMID 41154568, 2025). "The inflammatory response triggered by pneumonia involves a cascade of cytokines, including IL-6, TNF-α, and IL-1β, which contribute to endothelial dysfunction and myocardial stress." (PMID 40151738, 2025). "In detail, the key pro-inflammatory cytokine, IL-6, triggers the liver to produce CRP, which, in turn, promotes leukocyte recruitment and inflammatory signaling in endothelial cells, leading to endothelial dysfunction (ED)." (PMID 40722588, 2025). "Elevated inflammatory markers, such as interleukin-6 (IL-6) and tumor necrosis factor-alpha (TNF-α), have been observed in patients with PAD, contributing to endothelial dysfunction and plaque formation." (PMID 40909223, 2025). "Infection triggers a robust inflammatory response with high levels of cytokines like interleukin-6 (IL-6) and tumor necrosis factor-alpha (TNF-α), driving endothelial dysfunction and widespread tissue injury." (PMID 41158128, 2025). "Immunofluorescence staining revealed significant endothelial dysfunction and senescence in the HHcy-exposed rats, particularly in the Mid-old+HHcy group, as shown by decreased Laminb1, PCNA and increased p21, IL-6 expression." (PMID 41281764, 2025). "Emerging biomarkers of endothelial dysfunction, including neopterin, osteoprotegerin, fetuin-A, homocysteine, leptin, adiponectin, PAI-1, CRP, IL-6, and CECs, provide additional understanding of the pathophysiology of endothelial damage." (PMID 40529825, 2025). "This cascade stimulates the production of cytokines (e.g., IL-6, TNF-α), acute-phase proteins (e.g., CRP), and adhesion molecules, which collectively contribute to endothelial dysfunction and systemic inflammation." (PMID 40870942, 2025). "The mechanism includes increased systemic inflammation (C-reactive protein, IL-6, and TNF-α), hormone imbalance, and endothelial dysfunction." (PMID 41153819, 2025). "The ROS-induced oxidation of the IκB kinase complex activates nuclear factor kappa B (NF-κB), driving the transcription of proinflammatory cytokines (e.g., IL-6, TNF-α) and mediators of endothelial dysfunction." (PMID 40332110, 2025). "Recent evidence supports that periodontal inflammation contributes to systemic endothelial dysfunction and plaque instability through inflammatory mediators such as C-reactive protein (CRP), interleukin-6 (IL-6), and tumor necrosis factor-α (TNF-α)." (PMID 41303261, 2025). "The inflamed fatty liver produces pro-inflammatory cytokines (IL-6, TNF-α) and prothrombotic factors while decreasing hepatokines fetuin-A and adiponectin which leads to increased systemic inflammation and endothelial dysfunction and atherogenesis." (PMID 41431526, 2025).
endothelial dysfunction (continued). "Pro-inflammatory cytokines (IL-6, TNF-α, IL-17) and circulating immune complexes can promote endothelial dysfunction, leading to altered choroidal perfusion, increased vascular permeability, and secondary changes in retinal and choroidal thickness." (PMID 41374071, 2025). "Elevated levels of pro-inflammatory cytokines such as interleukin-6 (IL-6) and tumor necrosis factor-alpha (TNF-α) are commonly observed in CKD patients, contributing to renal fibrosis and endothelial dysfunction." (PMID 40217935, 2025). "First, cytokines such as IL-6, TNF-α, and IL-1β, which are typically elevated in malignancy, promote endothelial dysfunction, upregulate adhesion molecules, and activate platelets." (PMID 41583284, 2025). "Elevated Ang II promotes macrophage infiltration and stimulates excessive production of pro-inflammatory cytokines (e.g., IL-6, MCP-1) and adhesion molecules (e.g., VCAM-1), ultimately contributing to endothelial dysfunction." (PMID 41012594, 2025). "Elevated hs-CRP levels reflect heightened hepatic production in response to IL-6 and TNF-α, promoting endothelial dysfunction, arterial stiffness, and myocardial remodeling." (PMID 40065867, 2025). "CRP and IL-6 are acute-phase reactants elevated during systemic inflammation and platelet activation, whereas TNF-α is involved in promoting endothelial dysfunction, leukocyte adhesion, and vascular inflammation." (PMID 39857281, 2025). "Increased plasma levels of interleukin-6 (IL-6), C-reactive protein (CRP), and tumour necrosis factor-α (TNF-α) pinpoint systemic inflammation and contribute to endothelial dysfunction in cSVD." (PMID 40699631, 2025). "Chronic inflammation, marked by elevated cytokines (e.g., IL-6, TNF-α) and acute-phase reactants like CRP, accelerates endothelial dysfunction and plaque instability." (PMID 41202086, 2025). "Cytokines such as TNF-α, IL-6, IL-17A, CXCL9, CXCL10, and VCAM-1 are often elevated in both MASLD and SAH, playing crucial roles in immune cell recruitment, endothelial dysfunction, and fibrogenesis." (PMID 40977717, 2025). "Similarly, HTP use was associated with increased IL-8, IL-6, and IL-2 levels (p < 0.05), as well as higher white blood cell (WBC), leukocyte (p < 0.05), and eosinophil levels (p < 0.01), and an increase in the inflammatory response (p < 0.01), followed by endothelial dysfunction." (PMID 40868658, 2025). "The cytokine pattern observed in our oocyte-donation cohort—with increased IL-6, IL-1β, TNF-α, CXCL10, and VEGF—parallels these findings and supports the concept that immune activation and endothelial dysfunction are central to the disease process." (PMID 41561632, 2025). "Endothelial dysfunction contributes to inflammation by increasing vascular permeability and encouraging inflammatory cells (TNF-α, IL-6) to adhere to the endothelium." (PMID 40028266, 2025). "In addition, other emerging biomarkers-such as proadrenomedullin, soluble urokinase plasminogen activator receptor, and interleukin-6 may provide insight into the severity of infection, immune dysregulation, or endothelial dysfunction and warrant further investigation." (PMID 41343415, 2025). "As expected, mRNA expressions of the monocyte marker CD68, the endothelial dysfunction marker CD146, the monocyte chemoattractant protein-1 (MCP-1), and the interleukin-6 (IL-6), were significantly upregulated since 6 h of renal IR." (PMID 39707203, 2024). "Systemic inflammation, evidenced by increased levels of pro-inflammatory cytokines such as IL-6 and TNF-α, together with biomarkers of endothelial dysfunction such as PAI-1 and CRP, demonstrate a chronic inflammatory state present in MetS." (PMID 39728125, 2024). "Long night periodical hypoxia episodes determine inflammation with oxidative stress and release of systemic inflammatory mediators like TNF-α, IL-6, IL-8, and CRP, which lead to endothelial dysfunction and atherosclerotic plaque formation." (PMID 39585008, 2024).